MSLN (mesothelin)
Diseases named in the same sentence as MSLN in open-access papers (continued):
Sharing a sentence is not in itself a finding about the gene and the disease.
tumor (continued). "We then detected the level of HA in the tumor tissues by ELISA assay, and found that HA level was decreased in anti-MSLN-sP CAR-T cell treated groups compared with anti-MSLN CAR-T cell group." (PMID 34326835, 2021). "The MSLN protein is the antigen recognized by the mAb, K1, and is a good target for tumor-specific antibody-based therapies." (PMID 33670777, 2021). "The interaction of mesothelin with CA125 (cell surface glycoprotein) facilitates tumor invasion and metastasis." (PMID 34827604, 2021). "The role of MSLN in promoting tumor invasion and metastatic spread provides another argument to select MSLN as a target." (PMID 34439085, 2021). "Originally, T cells were engineered to transiently express anti-mesothelin CAR to avoid off-tumour on-target toxicity." (PMID 34226685, 2021). "Mesothelin is considered to be an attractive tumor antigen in that it has a very limited expression profile in healthy tissues, with the exception of cells lining pleura, peritoneum and pericardium, but a high expression in PDAC cells." (PMID 33710604, 2021). "Preconditioning of the TME with FRβ-specific CAR-T cells also improves the effectiveness of tumor-directed anti-mesothelin CAR-T cells, while simultaneous co-administration of both CAR products does not." (PMID 33563975, 2021). "Mesothelin independently activate epithelial-to-mesenchymal transition and tumor progression in some malignant tumors." (PMID 33832498, 2021). "In several types of cancer, aberrant expression of mesothelin has been shown to play a role in angiogenesis, apoptosis resistance as well as promoting tumor proliferation, invasiveness and metastasis." (PMID 34522225, 2021). "Using an anti-CD3ε mAb, anti-FOLR1 mAb, and anti-MSLN mAb, we examined the distribution of T cells and expression of FOLR1 and MSLN in tumor samples from mice by IHC analysis." (PMID 34803504, 2021). "Mesothelin expression and co-expression of mesothelin and CA125 were associated with tumor aggressiveness in several types of carcinomas." (PMID 33832498, 2021). "The average tumor volume in the Control-T group increased to 711.2 mm3, whereas those in the MSLN-CAR, FOLR1-CAR, and Tandem CAR-T groups were 227.1 mm3, 21.7 mm3, and 5.0 mm3, respectively (p <0.0001)." (PMID 34803504, 2021). "The use of anti-MSLN in xenograft mouse models significantly reduced tumor growth and metastasis accelerated by CA125." (PMID 33613114, 2021). "MSLN expression has been correlated with alterations in cell survival, proliferation, adhesion, and overall tumor progression." (PMID 34830322, 2021). "This MSLN-MUC16 interaction has been shown to be important for tumor cell adhesion and metastasis and is the main target of existing anti-MSLN immunotherapies, including anti-MSLN CAR T cell therapy." (PMID 33588928, 2021). "MM is a treatment-resistant tumor with few approved treatment options, however novel immunotherapeutic approaches have renewed hope for improved clinical outcomes, especially anti-MSLN CAR T cell therapy." (PMID 33588928, 2021). "Transcriptome analyses identified MSLN as a highly tumor-specific target in greater than 30% of pediatric AML patients." (PMID 34885074, 2021). "Mesothelin is a tumor differentiation antigen that is normally present on the mesothelial cells lining the pleura, peritoneum, and pericardium." (PMID 34926461, 2021). "Studies have identified MSLN as a promising tumour antigen in OC as it is overexpressed in over 75% of HGSOC tumours." (PMID 33800608, 2021). "MSLN knockdown in MPM results in reduced tumor growth and metastasis in vivo with the downregulation of stem cell and epithelial–mesenchymal-transition (EMT) genes." (PMID 34439085, 2021). "Upon binding, this monoclonal antibody elicits antibody-dependent cellular cytotoxicity (ADCC) and inhibits the adhesion of MSLN-expressing tumor cells to MUC16-expressing tumor cells." (PMID 34439085, 2021).
tumor (continued). "This was confirmed in a study using a human uterine xenograft tumor model expressing varying levels of MSLN, which illustrated that AR’s therapeutic response was correlated with the level of MSLN expression in the tumor cells." (PMID 34439085, 2021). "In order to translate our in vitro findings in an in vivo model, we assessed to what extent MSLN drives tumor growth and peritoneal dissemination in nude mice." (PMID 32612258, 2020). "In PDAC, MUC16 and MSLN expression is correlated, and this co-expression was shown to promote cell mobility and tumor invasion, especially through the activation of JNK and ERK pathways, and also through the matrix metalloproteinase (MMP)-7 activity." (PMID 32517181, 2020). "In this study we explored the therapeutic potency of a novel anti-Mesothelin antibody–drug conjugate (Anetumab ravtansine) as a function of Mesothelin expression in the targeted tumor cells." (PMID 32815024, 2020). "Choudhary and colleagues from the laboratory of Ira Pastan reported the synthesis of the first PE-based MSLN-targeted immunotoxin in 1998, and demonstrated anti-tumor activity in mice bearing human tumors expressing MSLN." (PMID 32605175, 2020). "For proof-of-concept we analyzed dose-dependent T-cell-mediated cytotoxicity on mesothelin (MSLN)-positive tumor cell lines NCIH596 (approx. MSLN ABS/cell) and AsPC1 (approx. MSLN ABS/cell) mediated by an analogous Prot-MSLN-TCB." (PMID 32581215, 2020). "Mesothelin, highly expressed in OC, plays important roles in cell adhesion, tumor metastasis, and drug resistance." (PMID 32983962, 2020). "Within the applied dose levels complete tumor regression was achieved only in tumors which expressed Mesothelin at particularly high levels (Hela cell tumors)." (PMID 32815024, 2020). "Tumor regressions were seen when SS1P was given as monotherapy to nude mice harboring human tumors expressing MSLN." (PMID 32605175, 2020). "The results revealed that YAP1 is directly connected to secreted AREG, CTGF, CYR61, FGF1 and MSLN that are involved in fibrosis and other key signaling pathways involved in the tumor-stroma interactions." (PMID 32054505, 2020). "Mesothelin is a tumor antigen that is highly expressed in several tumor types and plays a vital role in promoting proliferation and invasion." (PMID 33081383, 2020). "Mesothelin has been investigated as a target for molecular imaging probes designed to assess tumor uptake, distribution in primary tumor and secondary tumor sites, and response to treatment." (PMID 32983962, 2020). "The therapeutic response to the anti-Mesothelin ADC correlated closely with the level of Mesothelin expression in tumor cells." (PMID 32815024, 2020). "We then intraperitoneally transplanted ERC/mesothelin-overexpressing and control cells into mice, and examined the effect of ERC/mesothelin on mouse survival and tumor phenotype." (PMID 32677949, 2020). "Anti-tumor activity studies were performed in human uterine xenograft tumor models that express Mesothelin at high, moderate or low levels." (PMID 32815024, 2020). "Mesothelin is involved in the epithelium–mesenchymal transition, resistance to apoptosis and tumor invasion." (PMID 32235331, 2020). "Herein, MSLN CAR T-cells that expressed a tumor homing chemokine receptor CCR2 showed improved tumor infiltration." (PMID 32582537, 2020). "The results demonstrate a positive correlation between the level of Mesothelin expression in tumor cells and the sensitivity to the anti-Mesothelin ADC." (PMID 32815024, 2020). "Mesothelin as a tumor target is particularly interesting in gynecology since the female inner genital organs are formed by the middle germ layer, the mesoderm." (PMID 32815024, 2020). "MSLN and MUC16 co-expression, assessed by immunohistochemistry, was reported to be associated with increased tumor cell invasiveness and metastasis, and poor clinical outcomes of PDAC patients." (PMID 32517181, 2020).
tumor (continued). "The high-avidity binding to MSLN led to an enhanced selective killing of both moderate MSLN-expressing and high MSLN-expressing tumor cells both in vitro and in vivo." (PMID 32143496, 2020). "MSLN overexpression in cancers enables tumor-specific targeting using monoclonal antibodies, as well as chimeric antigen receptor (CAR)-T cells containing single-chain variable domain fragments (scFvs) that bind to MSLN." (PMID 32143496, 2020). "The results of these in vitro and in vivo studies indicate that MSLN-targeted iToxs have the potential for clinical anti-tumor activity if optimal combination strategies can be identified." (PMID 32605175, 2020). "Conversely, higher expression of MSLN in tumors is supposed to participate in cell adhesion, tumor progression, metastasis, and chemo-resistance." (PMID 32983962, 2020). "To explore the therapeutic potency and to optimize application regimes we performed dose-efficiency studies in three uterus derived human tumor models which express Mesothelin at variable levels." (PMID 32815024, 2020). "Immunotherapy targeting MSLN includes the use of tumor vaccines, antibody-based therapies, and adoptive T-cell therapy (CAR-T cells), some of which have demonstrated outstanding results in early clinical studies." (PMID 33344222, 2020). "The concordance rate of MSLN expression between the biopsy specimens and the frontal margin of the tumor was 87.4% (P < 0.0001), verifying the previously identified degree of homogeneity in MSLN expression." (PMID 33196692, 2020). "Tracer tumor uptake was also correlated with immunohistochemistry of MSLN expression on archival tumor tissue." (PMID 33081383, 2020). "As a conjugate to an anti-Mesothelin antibody Anetumab ravtansine bounds to Mesothelin and becomes internalized by Mesothelin-positive tumor cells." (PMID 32815024, 2020). "Mesothelin (MSLN) is a tumor differentiation antigen expressed in several solid neoplasms and a limited number of healthy tissues." (PMID 32174772, 2020). "Several tumor-antigen targets, such as MSLN, WT-1, FAP and the antigens of the ErbB family are evaluated for their applicability for CAR T-cell therapy in MPM." (PMID 32582537, 2020). "Mesothelin (MSLN), a glycosylphosphatidylinositol-anchored membrane glycoprotein, participates in cell adhesion, tumor progression, metastasis, and drug resistance." (PMID 32983962, 2020). "In vivo, the anti-tumor effect of MesobsFab depends upon a threshold of MSLN density on target cells." (PMID 31354732, 2019). "When multi-specific CAR-T cells were activated, cytokines were released and the tumor burden was reduced in both in vitro and in vivo experiments, similar to the single second generation of mesothelin-targeting CAR-T cells." (PMID 31754328, 2019). "Mesothelin (MSLN), a tumor-associated antigen broadly overexpressed on various malignant tumor cells, while its expression is generally limited to normal mesothelial cells, is an attractive candidate for targeted therapy." (PMID 31463062, 2019). "In mouse models of pancreatic cancer, MSLN overexpression promotes metastasis and proliferation of tumor cells." (PMID 31354732, 2019). "A third generation mesothelin CAR using ICOS/4-1BBζ showed significantly better tumor control and better T cell persistence than ICOSζ or 4-1BBζ CARs alone in a mesothelin-expressing pancreatic xenograft NSG mouse model." (PMID 30804938, 2019). "The thorium-227 anti-mesothelin monoclonal antibody conjugate radiopharmaceutical uses a 3,2-HOPO chelate to house thorium-227 and link it to a tumor-targeting antibody, and in this case, against mesothelin." (PMID 30984615, 2019). "MSLN expression was observed mainly at the tumour cell membrane but also in the cytoplasmic compartment." (PMID 31537838, 2019). "In contrast, preclinical and clinical studies showed that aberrant MSLN expression on tumor cells plays an important role in promoting proliferation and invasion." (PMID 31463062, 2019).
tumor (continued). "P4 CAR-T cells were shown to be able to lyse MSLN-positive tumor cells in vitro and in vivo, even in the presence of soluble MSLN protein." (PMID 31463062, 2019). "The anti-mesothelin scFv provides tumor-specific targeting while Hsp70 facilitates both innate and adaptive immune responses toward the tumor." (PMID 31320999, 2019). "An extra level of complexity resides in the fact that overexpression of mesothelin in immunocompetent mice has been shown to inhibit tumor formation." (PMID 31354732, 2019). "Since mesothelin was determined to be present in the tumor lysate, and expressed on the tumor cells of the patients, it was regarded to be a relevant antigen in this setting." (PMID 30245692, 2018). "Taken together, these data demonstrate that meso-CART cells recognized and killed mesothelin+ cells in a mesothelin-dependent manner and secreted Th1 cytokines in response to mesothelin+ tumor cells." (PMID 29568387, 2018). "The proliferation of SS1-Δζ-expressing T cells was very low even after stimulation with the tumor cells expressing high levels of MSLN (lower right column and B, open bar)." (PMID 30558663, 2018). "Therapy-induced T cell reactivity was assessed in peptide/MHC multimer stainings using mesothelin as a prototypic target antigen with confirmed expression in the clinical tumor lysate preparation." (PMID 30245692, 2018). "Pancreatic cancer exhibits a number of tumor-specific antigens, such as carcinoembryonic antigen, mesothelin, HER-2, and MUC1, which are promising applicants for testing CARs T-cell therapy." (PMID 29707526, 2018). "In contrast, in the MSLN-transfected HepG2 xenograft model, treatment with the CD47xMSLN biAb induced a significant increase of macrophages in the tumor." (PMID 30400822, 2018). "From a functional standpoint, data indicate mesothelin positively regulates tumor growth and invasion." (PMID 30319627, 2018). "In general, the type of cellular regulation described here integrates a cognate tumor antigen (e.g., MSLN) with a tumor surface molecule (e.g., αvβ3) presented on target cells." (PMID 29558951, 2018). "Because the average concentration of shed MSLN in the blood is ~6 nM in a tumor of ~300 mm3, 89Zr-amatuximab (1.75 nM) would be mostly bound to shed MSLN in blood during a 48 h period and this complex sequestered into liver and spleen." (PMID 29720923, 2018). "The expression of mesothelin on tumor cells plays an important role in tumor growth, survival, metastasis, and progression." (PMID 29568387, 2018). "Anetumab ravtansine showed potent anti-tumor activity in models with medium to high mesothelin expression (H-Score >50)." (PMID 30344925, 2018). "Changes in mesothelin, calretinin and podoplanin gene expression levels were also evaluated in tumor samples." (PMID 29527515, 2018). "Despite that a large number of candidate markers has been reported for MPM in the literature, mesothelin is still the best blood-based tumor marker available and the only one with FDA approval." (PMID 30008600, 2018). "Further mechanistic studies on MSLN are needed to validate the potential role of MSLN in tumor metastasis that possibly will provide insight for effective MSLN-targeting therapies for several cancers." (PMID 30134520, 2018). "Based on our results, cognate tumor cells expressing MSLN and CEA are required for dCAR-T cell activity, including activation, proliferation, and cytotoxicity." (PMID 30103775, 2018). "One example is Amatuximab, a chimeric high-affinity monoclonal IgG1/k antibody targeting MSLN, which elicits cellular toxicity against MSLN-expressing tumour cells, and reduces invasive capacity and tumour sphere formation." (PMID 30345394, 2018). "Our data indicate that FHBM can accurately control timing and dose of injected CAR-T cells, and sdCAR-T cells exert significant antitumor activity while releasing lower levels of cytokines for the cognate tumor cells expressing both MSLN and integrin αvβ3." (PMID 29558951, 2018).
tumor (continued). "Aberrant expression of mesothelin has been shown to promote tumor progression and metastasis through interaction with established tumor biomarker CA125." (PMID 29738555, 2018). "In summary, we have constructed meso-CART cells that secrete cytokines and exert cytotoxic effects in response to mesothelin-positive tumor cells both in vitro and in vivo." (PMID 29568387, 2018). "Although the cancer-specific expression of MSLN makes it a potential therapeutic target, more studies are needed to validate the role of MSLN in tumor metastasis." (PMID 30134520, 2018). "The cytotoxicity of T cells expressing this dual-receptor CAR was strictly dependent on the exogenous molecule FHBM in addition to cognate tumor cells expressing MSLN and integrin αvβ3." (PMID 29558951, 2018). "In the presence of cognate tumor cells (AsPC-1) expressing both CEA and MSLN, dCAR-T cells exerted high anti-tumor activity relative to that of other single-receptor CAR-T cells bearing only one signaling pathway (e.g., Cζ-CAR and MBB-CAR)." (PMID 30103775, 2018). "Variants 1.4.1 and 2.4.1 demonstrate specific affinity for the MSLN tumor marker present on the surface of tumor cells, and, upon MSLN binding, are internalized and co-localize with early endosomes." (PMID 29738555, 2018). "Supporting this notion knockdown of MSLN effectively inhibited liver and lung metastasis and migration and invasion of tumor cells." (PMID 28288645, 2017). "In conclusion, more than two-thirds of MPM patients have ≥50% distribution of MSLN-positive cells within whole tumor cells and, among the remaining one-third, half have ≥50% distribution of WT1-positive cells." (PMID 29100432, 2017). "Collectively, mesothelin participates in cell adherence, cell proliferation, tumor invasion of MPM, and plays an important role in monitoring the treatment response, the disease progression and the prognosis in MPM patients." (PMID 28507279, 2017). "Similar to C4d, other circulating biomarkers in MPM like mesothelin and activin A showed similar correlations with tumor load and stage of disease." (PMID 29184132, 2017). "Studies show that MSLN plays a role in cell adherence, survival, proliferation, tumour progression and chemotherapy resistance." (PMID 29059207, 2017). "It has also been shown that mesothelin plays a pivotal role in tumor cell proliferation, invasion, and chemotherapy resistance through the activation of oncogenic signaling." (PMID 28460459, 2017). "In MPM, two such candidate target TAAs are currently being investigated in clinical trials: mesothelin, which is overexpressed on the tumor cells, and fibroblast activation protein (FAP) that is overexpressed on tumor stromal cells." (PMID 28862644, 2017). "Because of this unique combination of high expression in different solid tumors and its complete absence from any vital normal tissues, mesothelin is being widely pursued for tumor-selective toxic payload delivery and cancer immunotherapy approaches." (PMID 29273809, 2017). "We therefore concluded that tumor-infiltrating lymphocytes harvested from patients with GBM contain T-cells that are able to react to mesothelin." (PMID 29113296, 2017). "The loss of malignant cells in the pleura fluid near 4 weeks post-cell infusion happened in one patient and another experienced stable to decreased burden of disease, suggesting anti-MSLN CAR-T cells possessed direct anti-tumor efficacy." (PMID 28466386, 2017). "Apart from mesothelioma, RG7787, is also a promising therapeutic agent for other solid tumor indications that highly express the tumor specific differentiation antigen mesothelin (MSLN), like ovarian and pancreatic cancer." (PMID 29273809, 2017). "In vivo results with the KB tumors suggested that reduced shedding of surface mesothelin by the paclitaxel treatment reduced decoy receptors produced by the tumor, ultimately increasing delivery of rIT." (PMID 28423727, 2017).